EGFR (epidermal growth factor receptor)
Diseases named in the same sentence as EGFR in open-access papers (continued):
Sharing a sentence is not in itself a finding about the gene and the disease.
tumor (continued). "Plasma ctDNA analyses have shown therapeutic benefits and can help understand tumor evolution, including mechanisms of resistance such as acquired ESR1 mutations that induce aromatase inhibitor resistance in BAC and EGFR resistance to 1st and 2nd generation EGFR tyrosine kinase inhibitors in NSCLC." (PMID 32188081, 2020). "Our data were consistent with above studies to a great extent, whereby low SUVmax of metastasis could predict EGFR mutations of NSCLC, while SUVmax of primary tumor was less useful." (PMID 32742498, 2020). "Research on primary tumor cells demonstrated that knockdown of USP8 expression or EGFR blockade could inhibit ACTH secretion effectively." (PMID 33537004, 2020). "There was a good correlation between the tumor uptake of the 89Zr-affibody and EGFR expression." (PMID 32560337, 2020). "In two other patients, EGFR T790M mutations were found in plasma but not in the matched tumor tissue." (PMID 32748806, 2020). "Moreover, coculture experiments demonstrate EGFR activation in tumor cells by myofibroblast-derived EGF, resulting in enhanced migratory and invasive properties in vitro." (PMID 32539768, 2020). "Twenty percent of the tumor cells showed weak expression of EGFR." (PMID 32979929, 2020). "Four of the five patients with a >50% reduction in tumor volume from baseline were EGFR amplified." (PMID 33187135, 2020). "This might be because EGFR activation leads to the suppression of the anti-tumour immune response via the induction of regulatory T-cells or reduction in the levels of T-cell chemoattractants, facilitating immune system evasion by tumour cells." (PMID 32034198, 2020). "Here, we investigate whether anti-lymphangiogenesis mechanisms contribute to the anti-tumour effects of EGFR-TKIs." (PMID 31892990, 2020). "Most of side effects of EGFR inhibitors in patients with tumor are tolerable." (PMID 33574751, 2020). "Thus, we tested combinatorial treatments of ipilimumab with an anti-EGFR aptamer endowed with anti-tumor activity, and constructed for the first time a novel bispecific immunoconjugate, made up of these two compounds." (PMID 32024070, 2020). "The receptors expressed by the tumors developed in vivo were not assessed, so EGF-conjugated GNPs were used as a potential more targeted tool for tumor cells in comparison to healthy cells, based on the increased expression of EGFR in tumor cells reported in literature." (PMID 33353068, 2020). "Activation of EGFR leads to the promotion of proliferation, differentiation, antiapoptotic signaling, angiogenesis, and metastatic spread and thus is highly correlated with tumor progression." (PMID 33456497, 2020). "Genetic variations in EGFR may alter protein function, contribute to tumor formation, and possibly alter the therapeutic efficacy of EGFR inhibitors." (PMID 33352891, 2020). "We demonstrated that local delivery of gemcitabine using GEM implants inhibited tumor cell growth by promoting c-CBL-mediated degradation of EGFR and inhibiting the proliferation, angiogenesis, and epithelial–mesenchymal transition of pancreatic/biliary tumors." (PMID 32111094, 2020). "EV EGFR levels positively correlated with tumour grade and with Ki67 tumour expression." (PMID 33143170, 2020). "Notably, a moderate reduction of percent tumor cells bearing membranous p-EGFR staining was observed (50% vs. 90% in the vehicle-treated MAPK1p.R135K mutant tumors)." (PMID 32351709, 2020). "The possible overlap and differences in the role FBLN1C/1D on EGFR function could extend the impact tumor microenvironments could have in regulating cell signaling and behavior in heterogenous lung tumors." (PMID 32719793, 2020). "As a result, EGFR appears to be a highly attractive target for tumor-specific therapies." (PMID 33552956, 2020). "Taniguchi K and Bai H demonstrated that both EGFR-mutated and non-mutated cell clones coexist in the same tumor." (PMID 32746896, 2020).
tumor (continued). "In summary, our study proposes that the activation of the EGFR/PI3K/AKT1/NRF2 pathway by HPV16 E7 leads to PIR/NF-κB activation in tumor oral epithelial cells, resulting in an increased cell migration, with the possibility remaining that this mechanism is involved in other epithelial cell models." (PMID 32679705, 2020). "However, combination therapy with gefitinib and CI-1040 significantly suppressed ~60% of tumor growth of CC cells by significant inhibition of both EGFR/AKT and ERK1/2." (PMID 32708604, 2020). "A xenograft tumor model was established to evaluate the role of 14-3-3ζ in EGFR-TKI resistance." (PMID 33123465, 2020). "The model also failed to incorporate other clinical and pathological prognostic factors (e.g., tumor markers, PET–CT value, and central or peripheral tumor) and some important recognized prognostic molecular factors (e.g., KRAS mutations, EGFR mutations, and ALK rearrangements)." (PMID 31884561, 2020). "Also, the acquired tumor resistance to TPCS2a-PDT likely occurs due to higher expression of the EGF receptor (i.e., EGFR) and loss of the MAPK/p38 inducing death pathway." (PMID 33552982, 2020). "Interestingly, the greatest tumor regression was shown after treatment with the engineered vaccinia viruses encoding scABs targeting both VEGF and EGFR (GLV-1h444), or VEGF and FAP (GLV-1h446)." (PMID 33167307, 2020). "Thus, targeting tumor cells expressing EGFR in a range of approximately 5,000–600,000 EGFR/cell, all three antibody-fusion proteins showed to be costimulatory active." (PMID 32504247, 2020). "Our results in this study showed that erlotinib as a single agent treatment has no anti-tumor activity in the LU0858 model with EGFR-mutation NSCLC." (PMID 32028611, 2020). "It consequently sensitized tumor cells to a panel of EGFR tyrosine-kinase inhibitors." (PMID 32575848, 2020). "However, this does not preclude EGFR-targeted radioimmunotherapy (RIT) of PnCa, since EGFR overexpression is used only to selectively deliver radiation to tumours." (PMID 33169241, 2020). "Furthermore, the EGFR‐CAR NK cells exerted a significant anti‐tumor effect on TNBC exhibiting upregulated EGFR expression in the two TNBC xenograft models." (PMID 32592435, 2020). "Some studies have shown that EGFR nanobodies anchored on exosomes via glycosylphosphatidylinositol (GPI) could bind to EGFR-expressing tumor cells with higher affinity." (PMID 33028046, 2020). "Tumours with strong EGFR expression had a larger number of blood and/or lymphatic vessels that could facilitate haematogenous and lymphatic dissemination of cancer cells." (PMID 32901137, 2020). "In advanced diseases, EGFR mutation detection is feasible in saliva, but with low sensitivity (46.2%) likely due to a low tumor content in tumors not proximal to airways." (PMID 33207539, 2020). "These biological drugs inhibit either the vascular endothelial growth factor A (VEGF-A) (i.e., bevacizumab), or the epidermal growth factor receptor (EGFR) (i.e., cetuximab and panitumumab), and can be chosen depending on RAS mutation status or primary tumor site." (PMID 33092032, 2020). "It is generally considered that the RNAi and shRNA cannot efficiently inhibit EGFR expression and the residual EGFR in cells may contribute to tumor development." (PMID 32413049, 2020). "EGFR-KDD was first described in NSCLC in 2015 following next generation sequencing of a tumour specimen derived from a patient that displayed durable response to erlotinib despite no detectable common EGFR mutations by a polymerase chain reaction-based assay." (PMID 31562956, 2020). "Different insertions demonstrated varied responses to EGFR TKIs, which suggests that the selective use of TKI to treat different EGFR e20ins might be useful for improving tumor responses." (PMID 32412152, 2020).
tumor (continued). "However, the Cox regression hazard model suggested that there is an association between tumor PD-L1 expression and PFS after the initiation of treatment with EGFR-TKI independently of EGFR mutation status." (PMID 33255696, 2020). "MiR-146b is a known tumor suppressor in many brain malignancies, with targets including tumor necrosis factor receptor (TNFR)-associated factor 6 (TRAF6), matrix metalloproteinase-16 (MMP16) and epidermal growth factor receptor (EGFR)." (PMID 32102476, 2020). "In the univariate regression analysis, smoking status, tumour histological type, Ki-67 expression level and the spectral CT quantitative parameters of the NIC in the AP and VP and λHU in the VP were significantly correlated with EGFR mutation status." (PMID 32103127, 2020). "In addition to ICM, the surface expression of the EGFR was examined in addition in the closed-loop flow system for heat treatment strategies of tumor cells with CH or MH alone and in combination with RT." (PMID 32349284, 2020). "Furthermore, EGFR has the ability to prevent the apoptosis of tumor cells by controlling the basal intracellular glucose level through sodium/glucose cotransporter 1, but this mechanism is normally inhibited when it is highly expressed as a result of cancer." (PMID 33273921, 2020). "Thus, tumor cells can transfer activated EGFR through EVs to the host macrophage to dampen innate immunity response, rendering the host immunocompromised." (PMID 32509768, 2020). "Inflammation is the best prognostic marker that a tumour is responding to EGFR inhibition therapy." (PMID 32054454, 2020). "Molecular analyses revealed that the tumor was negative for epidermal growth factor receptor mutations and anaplastic lymphoma kinase gene rearrangements and that 1%–24% of the tumor cells expressed PD‐L1." (PMID 33103845, 2020). "In addition, anti-EGFR Nb also shows tumor suppressing properties, which further enhance the efficacy of drug delivery." (PMID 33292202, 2020). "Our study also suggests the association between a low tumour content ratio and high false negative rates of EGFR identification in a small biopsy cohort in the cobas method." (PMID 32028905, 2020). "Mir-31 plays a significant role in activating the RAS signaling pathway, and high miR-31-3p expression could be the witness of the tumor’s EGFR independency and subsequently to its resistance to anti-EGFR therapy." (PMID 32825275, 2020). "Up-regulated UCH-L1 could promote the expression level of EGFR, thereby enhancing the invasion and metastasis abilities of tumor cells." (PMID 32042339, 2020). "Nevertheless, their findings suggest that EGFR+/ALK+ NSCLC patients could also benefit from ICI, especially EGFR+ patients with ≥25% PD-L1-expressing tumor cells." (PMID 32011450, 2020). "On the other hand, EGFR is involved in the electrotaxis of certain tumor cells." (PMID 32210363, 2020). "In particular, some of the most significant genes according to our approach, like FUBP1, NOTCH1, PTEN, EGFR, and NF1, were mutated in less than 10% of the patients within that tumor type, indicating that mutations in these genes are strongly associated with global changes in expression." (PMID 32732999, 2020). "Attention must be paid to false-negative results when conducting EGFR mutation detection with a sample containing cells other than tumor cells." (PMID 32033355, 2020). "Enhanced EGFR activity leads to increased expression of manganese-dependent superoxide dismutase (MnSOD), a ROS scavenging enzyme, and benefits tumor development by suppressing excessive ROS in tumor cells." (PMID 32226547, 2020). "We next tested PD-L1-CAR T cells in treating another PD-L1high, EGFR-mutant tumor cell line HCC827." (PMID 32792499, 2020).
tumor (continued). "It was later shown that targeting PD-L1 glycosylation by 2-DG combined with EGFR inhibition reduced tumor size and enhanced anti-tumor immunity mediated by 4-1BB, a glycoprotein receptor belonging to the tumor necrosis factor receptor superfamily, in syngeneic mouse models of TNBC." (PMID 32620165, 2020). "MAb806 is a novel anti-EGFR antibody that selectively targets a tumor-selective epitope." (PMID 33023139, 2020). "Efforts to map the relationships at work within the subcellular interactome of EGFR could help us fundamentally understand the mechanisms that govern tumor development and therapeutic resistance, leading to alternative treatment strategies." (PMID 32321917, 2020). "In regards to the detection of actionable EGFR mutations, both PFPE and FFPE tumour blocks performed equally with a total of n = 5 EGFR variants identified in both fixation types, present in 3 of 8 patients (37.5% of tumours sampled)." (PMID 31571426, 2020). "Finally, an EGFR Del19 aberration was found by tumor sequencing at diagnosis in one patient (FR068) but was missed by ctDNA assessment (not shown), demonstrating the limitations of ctDNA profiling and the possibility of false-negative results." (PMID 32748806, 2020). "Notably, also in vivo experiments on HSNCC xenograft tumor samples we observed an increased intracellular EGFR localization upon CDDP/CX treatment that was prevented by concomitant treatment with VPA." (PMID 33015030, 2020). "Therefore, MDM2 amplification activates multiple pathways and enables tumor cells to develop resistance to EGFR-TKIs." (PMID 32611363, 2020). "Basic science supported a key role of c-MET in NSCLC patients developing resistance to EGFR TKIs, supporting design of JNJ-61186372 (EGFR × c-MET BsAb) and patient selection criteria leading to demonstrated anti-tumor activity in NSCLC patients with resistance to EGFR TKIs." (PMID 32989604, 2020). "Taken together, our results indicate that EGFR activation via enhanced TGF-β signaling might play a critical role in tumor progression of OSCC by promoting cell survival." (PMID 33246423, 2020). "This implies that EGFR inhibitors may be more effective at suppressing dispersal than primary tumor growth." (PMID 32575848, 2020). "Considering the role of CTLA-4 in potentiating immune responses against cancer cells, and the new evidences suggesting the role of EGFR not only in the survival of tumor cells but also in the inhibition of immune system, we investigated the effects of the immunoconjugate also on the immune cells." (PMID 32024070, 2020). "Although EGFR-tyrosine kinase inhibitor (TKI) has low cerebrospinal fluid penetration rates, it may result in good intracranial response rates due to a high sensitivity of EGFR-mutant tumour to EGFR-TKI." (PMID 32298306, 2020). "Similarly, nimotuzumab and panitumumab also exert an anti-tumor effect by competitively binding to different regions of the EGFR extracellular region to inhibit downstream signaling pathways." (PMID 32793499, 2020). "A mutant form of EGFR, commonly called EGFRvIII or ΔEGFR, is only expressed in tumor cells." (PMID 33511267, 2020). "Although the expression of EGFR could frequently be observed in TNBC tumour tissue, the success of EGFR‐targeted regimens was reported, so far, to be insufficient in terms of sensitivity." (PMID 32558176, 2020). "Determination of EGFR T790M in tumour tissue and in cfDNA are both valid alternatives." (PMID 31598903, 2020). "Hence, studying activation/inactivation of the tumor-driving K-RAS/SIAH/EGFR pathway represents an opportunity to define therapy-responsive and prognostic K-RAS/SIAH-centered biomarkers in TNBC." (PMID 32846967, 2020). "Further, by inhibiting EGFR, which is necessary and sufficient for desmoplastic reaction, with cetuximab, this technique may provide an avenue of tumor penetration and destruction when coupled with chemotherapy." (PMID 32231028, 2020).
tumor (continued). "In addition, CD99CRIII3 dose-dependently inhibited EGFR dimerization only in wt-MDA-MB-231-originated tumor tissues." (PMID 33050232, 2020). "High expression rates of EGFR in high tumor categories support its role in tumor progression." (PMID 33202816, 2020). "Thus, treatments using a combination of EGFR inhibitors with surgery or conventional chemotherapy will target both the bulk of the tumor and the cancer stem cell subpopulation, thereby reducing the possibility of relapse and metastasis." (PMID 31823521, 2020). "We simulated free cetuximab, free EGFR, cetuximab-EGFR complexes, and the RO in both tumor areas." (PMID 33028895, 2020). "Interestingly, we found a similarity in the growth pattern of tumor cells and intensity of EGFR expression between 3-D cultures and tumor biopsies in all three samples." (PMID 33353547, 2020). "When YM155 and afatinib are combined, this may potentiate the inhibition of EGFR-mediated pathways, leading to enhanced inhibition of tumor cell proliferation and survival." (PMID 32001757, 2020). "In addition to activating the complement-dependent cytotoxicity (CDC), IgG1 EGFR monoclonal antibodies can also mediate ADCC to produce tumor killing effect." (PMID 32793499, 2020). "Furthermore, certain single-nucleotide polymorphisms (SNPs) of carbonic anhydrase 9 are associated with lower tumor stages and less lymph node involvement in LADC with wild-type EGFR." (PMID 33050100, 2020). "The level of EGFR expressions was high in tumor tissues than in the control tissues." (PMID 33273921, 2020). "In addition to controlling cell proliferation, activation of the EGFR axis can activate intracellular calcium signaling to induce tumor cell migration." (PMID 33042262, 2020). "EGFR is a transmembrane tyrosine kinase receptor that displays a maintenance act in signal transduction pathways including DNA repair, cell proliferation, tumor survival and invasion." (PMID 33680380, 2020). "Here, the anti-tumor efficacy of a protein (rLZ-8) from Ganoderma lucidum was evaluated, it was demonstrated that rLZ-8 could bind to EGFR specifically, drastically enter into Hepatoma cells, abrogate endosomal recycling and induce HCC cell death." (PMID 32079107, 2020). "In order to take into account possible inter-tumor heterogeneity of target expression, two different tumor cell lines were included: the A431 cell line that overexpresses EGFR and the scc- U8 cell line expressing moderate EGFR levels, which more closely resemble the in vivo levels." (PMID 32326519, 2020). "Therefore, many monoclonal antibodies and small molecule inhibitors target the EGFR in a clinical setting, inhibiting EGFR and decelerating tumor growth." (PMID 32733853, 2020). "In addition, our group showed that basal tumours are sensitive to epidermal growth factor receptor (EGFR) inhibition in vitro and in preclinical models." (PMID 33396795, 2020). "This fact could be understood as a compensatory mechanism to tumor-promoting influences of EGFR, Her2, Her3 and c-Met." (PMID 33202816, 2020). "Therefore, it can also be considered to be related to the mechanism of EGFR‐TKI (Tyrosine Kinase Inhibitor) resistance in tumor cells." (PMID 32875727, 2020). "In addition, overexpression of ANO1 promotes tumor growth by activating EGFR-mediated AKT/SRC/ERK1/2 signaling or Ras-Raf-MEK-ERK1/2 signaling pathway." (PMID 32899792, 2020). "However, the interaction between cancer cells and the microenvironment and the mechanisms of EGFR-TKI acquired resistance in tumour cells are rather complicated." (PMID 33287873, 2020). "Its determination is recommended, at least in native RAS tumours resistant to anti-EGFR." (PMID 32418154, 2020). "Various previous researches provided a rational explanation that the levels of epidermal growth factor receptor amplification and interleukin 6 could be upregulated by TERT promoter mutations, inducing tumor angiogenesis and necrosis." (PMID 32509858, 2020).